CD24 (CD24 molecule)
Diseases named in the same sentence as CD24 in open-access papers (continued):
Sharing a sentence is not in itself a finding about the gene and the disease.
oral squamous cell carcinoma (17 papers, 2013 to 2026). "The authors concluded that CD44 (high)/CD24 (low) represents cancer stem-like cells in oral squamous cell carcinoma." (PMID 38138858, 2023). "For instance, CD24 showed significantly lower expression in oral squamous cell carcinoma, while CD24 had higher expression in pancreatic intraepithelial neoplasia." (PMID 34774101, 2021). "In conclusion, both CD44 and CD24 were expressed in oral squamous cell carcinoma." (PMID 37664387, 2023). "Current study investigates the role of Oct4, Nanog and CD24 in locally-advanced oral squamous cell carcinoma (OSCC), to evaluate whether the expression of these markers can predict efficacy of neoadjuvant-chemo-radiotherapy and survival of patients." (PMID 32986350, 2020). "The simultaneous downregulation of F4/80+ and CD206+ TAMs, in addition to anti-CD24 mAb treatment, led to a noteworthy augmentation in the amount of CD4+ and CD8+ T cells within the tumour microenvironments (TMEs) of oral squamous cell carcinoma (OSCC)." (PMID 38137380, 2023). "This is consistent with previous studies showing that CD44v3+/CD24– and CD44v3+/ALDH1+ cells possess CSCs properties in human oral squamous cell carcinoma and HNSCC, respectively." (PMID 36528833, 2023). "Through controlling CD24, miR-146a/AKT/β-Catenin activation controls the cancer stem cell phenotype in oral squamous cell carcinoma." (PMID 37965067, 2023). "In the case of oral squamous cell carcinoma (OSCC), the application of anti-CD24 mAb resulted in the reduction in the number of tumour-associated macrophages (TAMs)." (PMID 38137380, 2023).
invasive breast carcinoma (16 papers, 2006 to 2025). A carcinoma that infiltrates the breast parenchyma. "To explore the clinical relevance of our findings, we conducted Spearman correlation analysis of the expression of CD24 and relevant chemokines in TCGA (The Cancer Genome Atlas) Breast Invasive Carcinoma dataset using cBioportal user interface." (PMID 40783744, 2025). "In contrast, a CD44(-) CD24 (+) phenotype is a poor prognostic marker in early invasive breast cancer." (PMID 24392029, 2013). "Analysis of pan-cancer expression for CEACAM6 and CD24 revealed that both levels were significantly altered in a number of cancer tissues compared to their respective normal counterparts, such as breast invasive carcinoma (BRCA), lung adenocarcinoma (LUAD), and thyroid carcinoma (THCA) 23-25." (PMID 40860182, 2025). "In invasive breast cancer, the authors found CD24 expression in 84.6% of cases." (PMID 24452533, 2014). "In consistent with our findings, a study showed that invasive breast cancer that express high levels of PD-L1 expressions positively regulate cancer stem cells that express CD44 high, CD24 low and OCT4high." (PMID 36604635, 2023). "However, while we found that CD24 expression decreased with advanced tumor progression and tumor grade both in MMTV-PyMT and in Apc1572T/+ mice, the expression of CD24 in late stage human invasive carcinoma of the breast is significantly increased in comparison with non-tumor tissue." (PMID 26978528, 2016). "Furthermore, the molecular and phenotypic analysis of primary invasive breast carcinomas revealed that CD24− and CD24+ subpopulations were present but this could not be correlated to any tumor characteristic." (PMID 23042145, 2012). "In lesions of invasive breast cancer, Mylona and colleagues showed a correlation between the CD44+/CD24- immunophenotype and negative lymph node metastasis and lower staged tumors." (PMID 23419168, 2013).
multiple myeloma (16 papers, 2014 to 2025). "CD24-positive myeloma cells represent a large fraction of residual myeloma cells after BCMA-CAR-T therapy." (PMID 38242888, 2024). "Their findings indicated that CD24 was found to be expressed in myeloma cells at relapse following BCMA CAR-T cell therapy." (PMID 38242888, 2024). "We find that CD24-CAR-T cells block the CD24-Siglec-10 pathway, thereby enhancing macrophage phagocytic clearance of myeloma cells." (PMID 38242888, 2024). "In vivo limiting dilution assays revealed that CD24+ myeloma cells showed a significantly higher tumor initiating capacity in NOD-Rag1null mice compared to CD24- fractions." (PMID 37744361, 2023). "An exception is multiple myeloma, where CD24 was rather downregulated compared with normal B‐cell cell lines." (PMID 34293822, 2022). "In our study, we have found elevated levels of CD24 in multiple myeloma, CLL and non-Hodgkin lymphoma compared to CD24 levels of healthy subjects." (PMID 34442367, 2021). "Regulatory B cells (Bregs) identified by the CD19+CD24+CD38+ phenotype are an important immunosuppressive components for myeloma, as they prevent immune effector cells from homing and interacting with targeted tumor cells." (PMID 33356013, 2021). "The highest levels of CD24/CD11b were found in multiple myeloma (39.1 ± 23.6), followed by chronic myeloid leukemia (33.0 ± 13.7) and non-Hodgkin lymphoma (32.3 ± 13.3)." (PMID 34442367, 2021). "Furthermore, it was observed that more myeloma cells expressed more frequently CD24 upon relapse subsequent to BCMA CAR-T cell therapy." (PMID 38242888, 2024). "After CD24-CAR-T treatment, we found a significant change in the ratios of M1Φ and M2Φ cells in the myeloma microenvironment." (PMID 38242888, 2024). "Residual myeloma cells following BCMA-CAR-T-mediated treatment show less-differentiated features and express stem-like genes, including CD24." (PMID 38242888, 2024). "Multiple Myeloma (MM) and Diffuse Large B‐cell Lymphoma (DLBCL) Germinal centre B‐cell‐like (GCB) presented low CD24 levels, whereas DLBCL Activated B‐cell‐like (ABC) showed a trend to express higher levels of CD24." (PMID 37654003, 2023). "CD24+CD38+ B cells in the bone marrow and peripheral blood of patients with multiple myeloma can inhibit the ADCC displayed by NK cells against myeloma cells." (PMID 35350071, 2022). "Especially, a high level of the CD24/CD11b score was found in subjects with CLL, non-Hodgkin’s lymphoma and multiple myeloma." (PMID 34442367, 2021). "Our results are consistent with previous studies demonstrating the role of CD24 in recurrent follicular lymphoma, in R-CHOP treatment response and tumor immunosuppression in diffuse large B-cell lymphoma and in multiple myeloma tumorigenicity." (PMID 34442367, 2021). "In this work, we develop CD24-CAR-T cells and test their ability to eliminate myeloma cells." (PMID 38242888, 2024). "The highest levels of CD24 were found in multiple myeloma (39.1 ± 23.6), followed by CLL (33.0 ± 13.7) and non-Hodgkin lymphoma (32.3 ± 13.3)." (PMID 34442367, 2021). "In B cells, CD24 shows no such interactions with the P-selectin ligand and may explain the distinction of myeloma from solid tumors." (PMID 31534632, 2019).
systemic lupus erythematosus (16 papers, 2011 to 2025). An autoimmune multi-organ disease typically associated with vasculopathy and autoantibody production. "The highly expressed CD24 on B cells is associated with several diseases, including small cell lung carcinoma and systemic lupus erythematosus." (PMID 36311013, 2022). "After 24 h of DW treatment, there was a noticeably decrease in frequency of CD19+ cells and increase in frequency CD19+ CD24+ CD27+, CD19+ CD24+ CD27+ IL-10+ Breg memory cells and CD19+ IL-10+ Bregs compared with untreated cells (lupus)." (PMID 40158179, 2025). "In contrast to individuals with rheumatoid arthritis or systemic lupus erythematosus, we found that expression levels of CD24 and CXCR3 on switched CD21+CD24+CD27+CD38intCD95+IgD− memory B cells were reduced in individuals with long-standing diabetes." (PMID 29881878, 2018). "To further determine which population of thymic CD4-CD8+ T cells was regulated by thymic B cells in lupus-prone mice, we first identified CD4-CD8+ T cell phenotype by analyzing CD3, RORγt, and CD24 expression in C57BL/6 and MRL/+ mice." (PMID 29163765, 2017). "In particular, Cluster #42 for cv-score of 0.7 is a subpopulation of mature neutrophils (defined as CD66ace+CD66b+) whose levels of expression for CXCR1, CD15, CXCR2, IgA, CD66ace, CD66b, CD10, CD45RO, CD24 and CD16 best distinguishes between Lupus patients and Healthy donors." (PMID 36191000, 2022). "RA patients also expressed significantly more IgG+veCD27−ve B cells that lacked expression of CD24, CD38, and CD21, which are akin to double negative 2 (DN2) B cells known to be associated with more severe, active systemic lupus erythematosus (SLE)." (PMID 32265907, 2020).
metastatic tumors (13 papers, 2003 to 2025). "The proportion of CD44+/CD24- tumor cells was significantly associated with lymph node involvement (P = 0.026) and PR status (P = 0.038), and was correlated with strong PR status in patients with recurrent or metastatic tumors (P = 0.046) and with basal-like features (p = 0.05)." (PMID 22762532, 2012). "ALB9 binds to CD24 at a different site from the P-selectin binding site, but still functions in the treatment of metastatic tumours, and therefore ALB9 offers promise for the subsequent treatment of metastatic tumours." (PMID 38137380, 2023). "This linkage was more prominent in samples from recurrent and metastatic tumors with more than 25% CD44+/CD24- cells." (PMID 22762532, 2012). "Studies have suggested that CD24 overexpression may contribute to the metastasis and subsequent poor prognosis of various metastatic tumors." (PMID 23946784, 2013). "In addition, silencing CD24 can inhibit the growth of metastatic tumors." (PMID 38914670, 2024). "We must also acknowledge that we were unable to confirm intratumor heterogeneity because there were only limited numbers of surgically resected specimens of the recurrent or metastatic tumors for repeat CD44/CD24 staining, which may be considered in future studies." (PMID 22839505, 2012). "All tumors are amenable to debulking surgery or wide local excision, and therefore, CD24-FIGS could aid in the complete resection of peritoneal disseminated and metastatic disease." (PMID 33260974, 2020). "HOXA10 is methylated in differentiated CD24-positive normal mammary cells and luminal BC cells, and the methylation level increases during the progression of BC from DCIS via a primary invasive ductal carcinoma, to a metastatic tumor." (PMID 27993161, 2016).
neuroblastoma (13 papers, 2013 to 2025). Neuroblastoma (NB) is the most common solid, extracranial childhood tumor. "Given that we examined the effect of exogenous addition of CD24 to a low-expressing neuroblastoma cell line (SK-N-AS), we also examined the impact of the loss of CD24 in a highly expressing neuroblastoma cell line." (PMID 38214542, 2024). "CD24 is commonly expressed in neuroblastomas and is associated with tumor differentiation and the emergence of anaplastic histologic features." (PMID 38214542, 2024). "Sensitivity to the tumoricidal effect of ZIKV on high-risk neuroblastoma tumors is dependent on CD24 expression, offering a prognostic marker for this oncolytic therapy in an extensive array of CD24-expressing cancers." (PMID 38214542, 2024). "The results revealed that both CD24 variant– 001 and variant– 007 mRNA transcripts were highly expressed in nearly all neuroblastoma cell lines tested, with the exception of theSK-N-AS cells where the CD24 variants were expressed at very low levels." (PMID 30044847, 2018). "A comparison of these poorly permissive cells to highly permissive neuroblastoma cells revealed a dramatic loss in the expression of the cell surface glycoprotein CD24 in poorly permissive cells." (PMID 30044847, 2018). "Genetic loss of PSGL-1 or CD24 and pharmacological inhibition of P-selectin reduced P-selectin binding to neuroblastoma cells in vitro." (PMID 29156825, 2017). "Functional assays further demonstrated that CD24 knockdown suppresses neuroblastoma cell proliferation, invasion, and migration." (PMID 41281650, 2025). "To validate CD24 as a feasible therapeutic target in neuroblastoma, we examined its expression in clinical specimens and neuroblastoma cell lines." (PMID 41281650, 2025). "Nevertheless, because CD24 is physiologically upregulated in developing neural tissue and neuroblastoma arises in early childhood, neurotoxicity warrants careful monitoring." (PMID 41281650, 2025). "In this study, we developed a CD24-targeted nanodrug delivery platform that co-delivers cystine and glucose oxidase (GOx) to induce disulfidptosis in neuroblastoma cells." (PMID 41281650, 2025). "In our experiments with ZIKV, we identified an alternative role for CD24 as a predictor of neuroblastoma permissiveness." (PMID 38214542, 2024). "Our previous reports indicated that the exogenous expression of CD24 in vitro increased the permissiveness of SK-N-AS neuroblastoma cells to ZIKV killing." (PMID 38214542, 2024). "Our previous work and that of collaborators identified a connection in neuroblastomas between CD24 expression, ZIKV specificity, and the regulation of intracellular antiviral pathways such as type I IFN, NFκB, and Ras." (PMID 38214542, 2024). "CD24, abundant in all neuroblastoma tumors, appears to be a predictor of neuroblastoma cells’ permissiveness to ZIKV infection." (PMID 38675903, 2024). "This laboratory's prior experimentation indicated that CD24 is necessary for the permissiveness of ZIKV in vitro using neuroblastoma cell lines." (PMID 38214542, 2024). "We investigate irAEs of an effective whole cell neuroblastoma vaccine and subsequently the effect of CD24-Fc, a CD24 and Fc fusion protein, on both the vaccine efficacy and induced irAEs in a mouse neuroblastoma model." (PMID 37346042, 2023). "Despite dampening these immune related adverse tissue specific events, appropriate timing of CD24-Fc administration can still maintain sufficient immunotherapeutic effect of vaccination in the mouse neuroblastoma model." (PMID 37346042, 2023). "We studied two vaccine strategies in mouse neuroblastoma models to evaluate the influence of CD24-Fc on the therapeutic effect of the vaccine." (PMID 37346042, 2023). "Restoration of CD24 expression in the Zika virus–immune neuroblastoma cell line SK-N-AS increased the oncolytic potential of Zika virus compared to its effect on the CD24-defective cell line." (PMID 37896752, 2023).
neuroblastoma (continued). "Transcriptomics analysis revealed that host cellular protein CD24 was present at moderate to high levels in the ZIKV-permissive neuroblastoma cell lines (e.g., IMR-32, CHLA-42, SMS-KAN)." (PMID 36016357, 2022). "Previous studies showed that the neuroblastoma cell line SK-N-AS (expressing low levels of cellular protein CD24) was highly restricted for ZIKV infection, and that this restriction was relieved by ectopic expression of CD24." (PMID 36016357, 2022). "Our results have implications for the possible use of CD24 as a biomarker for permissivity to viral infections, at least in neuroblastoma cells." (PMID 36016357, 2022). "Together, these data support our model that CD24 expression dampens the overall basal antiviral state of neuroblastoma cells through changes to intracellular factors that affect permissivity to virus infection." (PMID 36016357, 2022). "In conclusion, our results show that the expression of CD24 in a neuroblastoma cell line alters both the basal antiviral state of the cells and responses to IFN-I, resulting in increased permissivity to infection by three different RNA viruses." (PMID 36016357, 2022). "This further suggests that CD24 is necessary for the production of Zika viral NS1 protein in neuroblastoma cells." (PMID 30044847, 2018). "In neuroblastoma, CD24 is often highly expressed and isoforms have been discovered in various tissues during the differentiation process, with their differences often reflecting variations in the extent of their glycosylation." (PMID 30044847, 2018). "In neuroblastoma CD24 is highly expressed in undifferentiated tumors and the expression of CD44 is correlated with better prognosis." (PMID 29156825, 2017). "CD24 expression as measured by all four probes was higher in neuroblastomas compared to the more differentiated ganglioneuroma and ganglioneuroblastoma samples." (PMID 29156825, 2017). "Further, flow cytometric measurement determined the level of PSGL-1 in neuroblastoma cell lines to be more modest in comparison with CD24 and CD44." (PMID 29156825, 2017). "Here, we confirm CD24 overexpression in neuroblastoma and explore its functional role: CD24 knockdown partially suppresses malignant behavior, but directly targeting CD24 for inhibition alone may be suboptimal, as knockdown effects are modest." (PMID 41281650, 2025). "To conclude, we investigate ICD signatures following oZIKV infection of paediatric brain tumour cells and propose TNF-alpha as a potential prognostic marker for brain tumour oZIKV therapy, with the only other known prognostic marker being CD24 for neuroblastoma oZIKV therapy." (PMID 40240536, 2025). "•Identified CD24 as a therapeutic target in neuroblastoma and built CD24-targeted exosome mimetics." (PMID 41281650, 2025). "CD24 is highly expressed in neuroblastoma and correlates with poor clinical prognosis." (PMID 41281650, 2025). "Furthermore, changes in intracellular antiviral pathways were observed by Kedarinath and colleagues after the modulation of CD24 in neuroblastoma cells in vitro." (PMID 38214542, 2024). "The results indicated robust expression of CD24 in the neuroblastoma patient sample, comparable to the levels seen in previously sensitive IMR-32 cells, predicting sensitivity to viral killing (as opposed to SK-N-AS cells, whose low expression of CD24 indicated resistance to viral killing)." (PMID 38214542, 2024). "That being said, the expression of CD24 was found to be robust in all of the neuroblastoma tumors." (PMID 38214542, 2024). "We further addressed the relevance of CD24 in neuroblastoma by modulating its expression in vivo." (PMID 38214542, 2024). "Assessments from both primary pretreatment and recurrent posttreatment isolates confirmed that permissive sensitivity to ZIKV killing was dependent on the expression of CD24, which was highly expressed in neuroblastomas and conferred a proliferative advantage to tumor growth." (PMID 38214542, 2024).